ATXN3 (ataxin 3)
Diseases named in the same sentence as ATXN3 in open-access papers (continued):
Sharing a sentence is not in itself a finding about the gene and the disease.
neuroblastoma (23 papers, 2015 to 2024). Neuroblastoma (NB) is the most common solid, extracranial childhood tumor. "Human neuroblastoma SK-N-SH cells expressing mutant ataxin-3 protein with 78 CAG repeats (MJD78) were employed as an in vitro model." (PMID 39472629, 2024). "ATXN3 knockdown substantially increased the accumulation and phosphorylation of TDP-43 CTFs, whereas ATXN3 overexpression reduced these phenotypes in human neuroblastoma cells." (PMID 36737438, 2023). "In neuroblastoma cells (N2a) expressing mutant ataxin-3, cordycepin treatment (20 μM) reduced the levels of the protein, while it did not interfere with the levels of non-expanded ataxin-3 (both wild-type ataxin-3 human and mouse endogenous ataxin-3)." (PMID 37108570, 2023). "To explore the potential of JM17, RTA-408, and DMF for treating SCA3, we used wild-type SK-N-SH neuroblastoma cells (WT) and SK-N-SH cells containing either 26 or 78 glutamines in the ataxin-3 gene, termed MJD26 and MJD78 cells hereafter." (PMID 35883884, 2022). "Carbobenzoxy-L-leucyl-L-leucyl-L-leucinal (MG132), a proteasome inhibitor, was used to treat human embryonic kidney 293 cells (HEK-293) and neuroblastoma SH-SY5Y cells expressing mutant ataxin-3 proteins." (PMID 33509239, 2021). "This in vitro model was generated by expressing an expanded form of human ataxin-3 in mouse neuroblastoma cells." (PMID 32272938, 2020). "Here, we used neuroblastoma cell and transgenic mouse models to examine the effects of truncated mutant ATXN3 on mitochondria functions." (PMID 28676741, 2017). "We transfected these four constructs into N2a neuroblastoma cells, and confirmed the expression level of ATXN3 via Western blotting." (PMID 28676741, 2017). "The ATXN3 constructs, described in this study, have been sub-cloned into expression vectors and transfected human neuroblastoma SK-N-MC cells have been analyzed for expression of RNA toxicity markers (manuscript in preparation)." (PMID 26270660, 2015). "Additionally, mitochondrial deficits were previously observed in a cellular model of MJD (neuroblastoma cells expressing ATXN3-78Q), showing increased sensitivity to rotenone, which suggested mitochondrial respiration defects." (PMID 37830611, 2023). "Truncated mutant ATXN3 was shown to cause mitochondrial dysfunction, further leading to neurodegeneration in both neuroblastoma cells and in cerebellum of transgenic mice, suggesting that truncated mutant ATXN3 has a more severe effect than full-length mutant one." (PMID 37830611, 2023). "In this study, neuroblastoma cells (SK-N-SH) was transduced to express either non-pathogenic ataxin-3-26Q or pathogenic ataxin-3-78Q proteins." (PMID 27469193, 2016). "In this study, we used in vitro neuroblastoma cells and in vivo transgenic mouse models to examine the effects of truncated mutant ATXN3 on mitochondrial functions, and showed that truncated mutant ATXN3 exacerbated above functions, further leading to neurodegeneration." (PMID 28676741, 2017). "Early reports in human neuroblastoma SK-N-SH and monkey COS7 cells indicated that mutant ataxin-3 (ATXN3) with 78 glutamines decreases the reduced/oxidized glutathione ratio (GSH/GSSG), an indicator of oxidative stress and cellular health." (PMID 34573082, 2021). "(A) Nuclear extract (NE), and cytosolic extract (CE) were purified from human neuroblastoma SH-SY5Y cells and the protein fractions were analyzed by western blots (WBs) to detect HTT, ATXN3, PNKP, and HAP1 levels in these sub-cellular fractions." (PMID 30994454, 2019). "Ataxin-3 gene carrying 82 polyglutamine residue fused with GFP protein are constructed previously (Ataxin-3 T-Q82) and we confirmed that overexpression of Ataxin-3 T-Q82 gene make protein aggregation in SH-SY5Y human neuroblastoma cells (unpublished data)." (PMID 26751205, 2016).
neuroblastoma (continued). "Studies have reported that ATXN3 protein regulates the BCL2L1 and BAX protein complex, exerting protective effects against H2O2-induced oxidative stress in HeLa (human adenocarcinoma) and SH-SY5Y (human neuroblastoma) cells." (PMID 38539908, 2024). "Indeed, we found that small hairpin RNA (shRNA)-mediated ATXN3 knockdown results in the substantial accumulation and hyperphosphorylation of TDP-43 CTFs at S409/S410 in HEK293T cells and SH-SY5Y neuroblastoma cells." (PMID 36737438, 2023). "Recent studies reported that oral squamous cell carcinoma (OSCC), testicular cancer (TC), colon cancer, breast cancer (BC), anaplastic thyroid carcinoma (ATC), neuroblastoma (NB), non-small cell lung cancer (NSCLC), and breast cancer stem cells were closely related to ATXN3." (PMID 36159990, 2022).
amyotrophic lateral sclerosis (20 papers, 2013 to 2024). Amyotrophic lateral sclerosis (ALS) is a neurodegenerative disease characterized by progressive muscular paralysis reflecting degeneration of motor neurons in the primary motor cortex, corticospinal tracts, brainstem and spinal cord. "MARCH5 also plays a role in the degradation of mSOD1 associated with amyotrophic lateral sclerosis, in the disposal of mutated ataxin-3 causative for Machado–Joseph disease as well as the clearance of S-nitrosylated MAP1B-light chain 1 linked to neuronal degeneration." (PMID 24133412, 2013). "Furthermore, in the experimental validation of 3′aTWAS-identified genes, we find that modulation of ataxin-3 (ATXN3), a 3′aTWAS susceptibility gene for amyotrophic lateral sclerosis (ALS), substantially impacts pathological hallmarks of ALS in vitro." (PMID 36737438, 2023). "Furthermore, we discovered ATXN3 as a 3′aTWAS-significant gene for amyotrophic lateral sclerosis, and its modulation substantially impacted pathological hallmarks of amyotrophic lateral sclerosis in vitro." (PMID 36737438, 2023). "Interestingly, reduced proteasomal degradation due to mutations in p97 have been found in the muscle wasting phenotype of amyotrophic lateral sclerosis (ALS) and cachexia, suggesting an important role for ATXN3 and the p97 complex in muscle physiology." (PMID 38716888, 2024).
Friedreich ataxia (20 papers, 2010 to 2026). An inherited condition that affects the nervous system and causes movement problems. "In European natives, pathogenic mutations should be searched in genes producing SCA1 (ATXN1), SCA2 (ATXN2), SCA3 (ATXN3), SCA6 (CACNA1A), SCA7 (ATXN7), SCA 12 (PPP2R2B), fragile X tremor ataxia syndrome (FMR1), SCA17 (TBP), CANVAS syndrome (RFC1), and Friedreich ataxia (FXN) [53﻿]." (PMID 35986227, 2023).
hereditary ataxia (16 papers, 2014 to 2026). An instance of an atactic disorder that is caused by an inherited genomic modification in an individual. "In patients with suspected hereditary ataxia, we identified expansions in loci that had not been assessed as part of routine diagnostic workup within the NHS at the time of recruitment, including ATN1, ATXN2, ATXN3, ATXN7, CACNA1A, FXN, TBP, and HTT." (PMID 35182509, 2022).
breast carcinoma (15 papers, 2016 to 2024). "Importantly, TSPAN8 and ATXN3 expression levels were associated with poor prognosis in breast cancer patients." (PMID 31253779, 2019). "ATXN3 also contributes to the development and progression of breast cancer, lung cancer, gastric cancer, colorectal cancer, and testicular cancer." (PMID 34322387, 2021). "These experiments strongly suggest that TSPAN8 together with ATXN3 promote the Hedgehog signaling and breast cancer progression by enhancing PTCH1 and SHH expression." (PMID 31253779, 2019). "In breast cancer, high expression of both ATXN3 is correlated with a poor prognosis." (PMID 37349820, 2023). "ATXN3 has been reported to play an important role in the development and progression of multiple types of cancers, including breast cancer, anaplastic thyroid carcinoma, testicular cancer, and non–small cell lung adenocarcinoma, in a tumor cell–intrinsic manner." (PMID 38038129, 2023). "ATXN3 promotes breast cancer metastasis by stabilizing KLF4 through deubiquitination." (PMID 37349820, 2023). "Additionally, ATXN3 was highly expressed in breast cancer and it promotes tumor tissue metastasis by deubiquitinating and stabilizing KLF4." (PMID 34482818, 2021). "Similarly, depletion of TSPAN8 or ATXN3 in primary cancer cells derived from breast cancer patients decreased these cells sphere formation efficiency and enhanced their sensitivity to chemotherapeutic agents." (PMID 31253779, 2019). "In addition, a positive association between the expression levels of TSPAN8 and SHH, as well as between PTCH1 and ATXN3, in breast cancer specimens was observed." (PMID 31253779, 2019). "In addition, the high levels of ATXN3 expression were correlated with poor prognosis in breast cancer patients." (PMID 31253779, 2019). "Accordingly, the expression levels of TSPAN8, SHH, Patched1, and ATXN3 were positively correlated in human breast cancer specimens, and the high expression levels of TSPAN8 and ATXN3 correlated with poor outcome of the patients." (PMID 36768876, 2023). "Consistently, high expression of ATXN3 and KLF4 serve as indicators of an adverse prognosis in breast cancer." (PMID 34575114, 2021). "At the same time, ATXN3 deubiquitinates and stabilizes KLF4, a closely related member of KLF5, enhancing cell migration and lung metastasis in breast cancer." (PMID 34575114, 2021). "An in vitro and in vivo study performed by Zhou and colleagues showed that breast cancer cell metastasis is promoted by ATXN3 (Ataxin-3, ATX3, AT3 or MJD), which is a novel deubiquitinating enzyme of KLF4." (PMID 33266506, 2020). "Our analyses of human breast cancer specimens revealed positive correlation among the expression levels of TSPAN8, PTCH1, SHH, and ATXN3." (PMID 31253779, 2019). "To determine the clinical relevance of TSPAN8- and ATXN3-regulated PTCH1/SHH stability, we performed IHC staining of 90 breast cancer specimens and found that the expression of TSPAN8 in the tumor tissue was higher than that in the adjacent non-tumor tissue." (PMID 31253779, 2019). "Accordingly, expression levels of TSPAN8, PTCH1, SHH, and ATXN3 are positively correlated in human breast cancer specimens, and high TSPAN8 and ATXN3 expression levels correlate with poor prognosis." (PMID 31253779, 2019). "Ataxin-3 deubiquitinates KLF4, stabilising the protein, and promoting breast cancer metastasis." (PMID 38497605, 2024). "Ataxin-3 has been shown to deubiquitinate and therefore stabilise KLF4, and it is hypothesised that the up-regulation of ATXN3 observed in breast cancer contributes to up-regulation of KLF4, thereby accelerating breast cancer metastasis." (PMID 38497605, 2024). "However, the mechansims of ATXN3 up-regulation in breast cancer, how KLF4 promotes breast cancer, and whether aberrant deubiquitination of KLF4 by ataxin-3 is involved in the pathophysiology of MJD, remain to be explored." (PMID 38497605, 2024).
autosomal dominant cerebellar ataxia (12 papers, 2014 to 2025). A clinically and genetically heterogeneous group of neurodegenerative diseases characterized by a slowly progressive ataxia of gait, stance and limbs, dysarthria and/or oculomotor disorder, due to cerebellar degeneration in the absence of coexisting diseases. "SCA3 is the most common autosomal-dominant cerebellar ataxia worldwide, and it is caused by a mutation in the ATXN3 gene." (PMID 38673907, 2024).
cerebellar degeneration (8 papers, 2015 to 2024). Degeneration of the cerebellum. "The acquisition of Purkinje cells from SCA3-iPSCs will further elucidate how the mutant ATXN3 selectively causes cerebellar degeneration." (PMID 31687087, 2019). "A link between ataxin-3 and PNKP thus reinforces the importance of DNA repair in maintaining healthy cerebellar neurons and suggests targets for therapy development for SCA3 cerebellar degeneration, with possible application to other cerebellar degenerative diseases." (PMID 25633989, 2015).
lung cancer (8 papers, 2014 to 2025). A malignant neoplasm involving the lung. "In fact, STAT3 interaction with ATXN3 was detected in transiently transfected HEK293T cells as well as endogenously in human lung cancer A549 cells." (PMID 38038129, 2023). "Fifth, importantly, reconstitution of PD-L1 expression partially reversed tumor growth of ATXN3-null syngeneic lung cancer." (PMID 38038129, 2023). "We then validated the potential role of ATXN3 in regulating tumoral PD-L1 expression in mouse and human lung cancer cells." (PMID 38038129, 2023). "To support this notion, we confirmed endogenous interaction of ATXN3 with HIF-2α in human lung cancer A549 cells." (PMID 38038129, 2023). "Through deubiquitinating transcription of KLF4, ATXN3 is responsible for inducing lung cancer development." (PMID 33613103, 2021). "Furthermore, in testicular and non‐small cell lung cancers, ATXN3 facilitates tumorigenesis by inhibiting the transcriptional activity of PTEN, a critical tumour suppressor gene." (PMID 40995818, 2025). "Notably, ectotrophic expression of both IRF1 and STAT3 largely restored IFN-γ–induced PD-L1 expression in ATXN3-null lung cancer cells." (PMID 38038129, 2023). "The endogenous interaction between IRF1 and ATXN3 was further confirmed in human lung cancer A549 cells, indicating that ATXN3 may enhance IFN-γ–induced PD-L1 expression through IRF1." (PMID 38038129, 2023). "Ataxin-3 also restricts transcription of PTEN in lung cancers." (PMID 32982735, 2020). "ATXN3 has been shown to restrict PTEN transcription in lung cancer cells." (PMID 26079537, 2015). "Moreover, the PTEN expression in lung cancer cells is regulated by deubiquitylase Ataxin-3." (PMID 37631304, 2023). "To further validate our findings in samples from patients with cancer, we first assessed mRNA expression levels of ATXN3 and CD274 in 22 lung cancer patients and found a positive correlation between ATXN3 and CD274 expression." (PMID 38038129, 2023). "In this case, combination therapy, with Ataxin-3 inhibitors and HDAC inhibitors, is a realistic strategy for PTEN-inhibited lung cancers." (PMID 32982735, 2020). "Though lung cancer cells (A549) treated with vorinostat (SAHA), a broad HDAC inhibitor, only shows limited response, PTEN induction is enhanced with Ataxin-3 depletion significantly." (PMID 32982735, 2020). "Indeed, the protein expression levels of ATXN3, PD-L1, IRF1, and HIF-2α were all elevated in both lung cancer and melanoma compared with their adjacent normal tissues." (PMID 38038129, 2023). "However, targeted ATXN3 deletion did not affect LLC1 lung cancer cell growth and colony formation, largely excluding the possibility that ATXN3 promotes LLC1 cancer cell growth." (PMID 38038129, 2023).
Anxiety (6 papers, 2013 to 2024). Intense feelings of nervousness, tension, or panic often arise in response to interpersonal stresses. "Overall these results suggest that control mice displayed a hyperactive phenotype associated with a reduced anxiety as compared to non-injected wild-type mice, which was prevented upon mutant ataxin-3 silencing." (PMID 25144231, 2014). "Another group reported similar findings, with no adverse effects on Atxn3 knockout mouse life span or fertility and no apparent abnormalities, but they did report apparent increased anxiety and increased levels of ubiquitinated proteins in the Atxn3 knockout model." (PMID 31683630, 2019).
spinocerebellar ataxia type 2 (6 papers, 2012 to 2024). A subtype of type I autosomal dominant cerebellar ataxia (ADCA type I) characterized by truncal ataxia, dysarthria, slowed saccades and less commonly ophthalmoparesis and chorea. "Spinocerebellar ataxia type 2 (SCA2) and type 3 (SCA3) are PolyQ diseases in which the Ataxin-2 and Ataxin-3 proteins, respectively, contain an abnormal polyQ tract prone to aggregate." (PMID 33530161, 2021).
testicular cancer (6 papers, 2020 to 2024). A primary or metastatic malignant neoplasm that affects the testis. "They demonstrate how Ataxin-3 can be both a promising biomarker and therapeutic target for testicular cancer." (PMID 32982735, 2020). "Recent research showed that non-small-cell lung cancer is related to Ataxin-3, so are testicular cancer and human colon cancer." (PMID 32982735, 2020). "The downregulation of ATXN3 could also inhibit the proliferation of testicular cancer cells by inhibiting AKT activation." (PMID 34322387, 2021). "ATXN3 is highly expressed in testicular cancer that promotes cancer cell proliferation." (PMID 33613103, 2021). "In testicular cancer, Ataxin-3 overexpression can promote cell multiplication." (PMID 32982735, 2020).